TAS2R4 (taste 2 receptor member 4)
Description:
Gustducin-coupled receptor for denatonium and N(6)-propyl-2-thiouracil implicated in the perception of bitter compounds in the oral cavity and the gastrointestinal tract. Signals through PLCB2 and the calcium-regulated cation channel TRPM5. In airway epithelial cells, binding of denatonium increases the intracellular calcium ion concentration and stimulates ciliary beat frequency.
Synonyms: T2R4
Tractability: Antibody: its Gene Ontology location is reachable by antibodies, with high confidence; UniProt predicts a signal peptide or a membrane-spanning region. PROTAC: a small molecule that binds it is known.
Target class: Membrane receptor; Taste receptor (taste family GPCR); Taste family G protein-coupled receptor
Gene: Protein-coding gene on chromosome 7 (141,776,674 to 141,781,691, forward strand). Ensembl gene ENSG00000127364.
Subcellular location: Membrane; Cell projection, cilium membrane
Pathways (Reactome):
Signal Transduction: Class C/3 (Metabotropic glutamate/pheromone receptors); G alpha (i) signalling events
Sensory Perception: Sensory perception of sweet, bitter, and umami (glutamate) taste
Gene Ontology:
Molecular function: bitter taste receptor activity; taste receptor activity; G protein-coupled receptor activity
Biological process: detection of chemical stimulus involved in sensory perception of bitter taste; G protein-coupled receptor signaling pathway; sensory perception of taste; signal transduction
Cellular component: membrane; plasma membrane; ciliary membrane
Genetic constraint (gnomAD): Loss-of-function variants: 17 observed, 14.72 expected, observed/expected ratio (o/e) 1.15, 90% interval 0.79 to 1.7. The upper end of that interval is the gene's LOEUF score, 1.7, which puts it in group 6 of 6, group 1 being the genes least tolerant of losing a copy. Missense variants: 297 observed, 355.88 expected, observed/expected ratio (o/e) 0.83, 90% interval 0.76 to 0.92. Synonymous variants: 129 observed, 144.14 expected, observed/expected ratio (o/e) 0.89, 90% interval 0.77 to 1.04.
Homologues: Orthologues: chimpanzee TAS2R4 (99% identical), macaque TAS2R4 (95% identical), dog TAS2R4 (75% identical), pig TAS2R4 (70% identical), guinea pig TAS2R4 (69% identical), mouse Tas2r108 (67% identical), rabbit TAS2R4 (66% identical), rat Tas2r108 (64% identical), tropical clawed frog tas2r7 (27% identical), tropical clawed frog tas2r4 (27% identical), tropical clawed frog t2r10 (25% identical), tropical clawed frog t2r2 (25% identical), and 10 more. Paralogues in human: TAS2R7 (32% identical), TAS2R3 (30% identical), TAS2R39 (30% identical), TAS2R41 (29% identical), TAS2R9 (28% identical), TAS2R40 (27% identical), TAS2R8 (26% identical), TAS2R10 (25% identical), TAS2R50 (25% identical), TAS2R14 (25% identical), TAS2R31 (25% identical), TAS2R38 (25% identical), and 11 more.
Diseases named in the same sentence as TAS2R4 in open-access papers:
TAS2R4 is named in the same sentence as 18 diseases in open-access papers, as found by Europe PMC text mining. Sharing a sentence is not in itself a finding about the gene and the disease. The quoted sentences say what the papers report.
breast carcinoma (6 papers, 2017 to 2025). "Singh and colleagues found significant differences in the expression levels of TAS2Rs in different types of breast cancer cell lines, such as decreased mRNA expression levels of TAS2R4 and increased mRNA expression levels of TAS2R14." (PMID 38999959, 2024). "TAS2R4 is expressed at higher levels in normal mammary epithelial cells compared with breast cancer cells, and only 5 of the 25 TAS2Rs levels were found to be down-regulated in the invasive breast cancer cell lines that were examined." (PMID 28467517, 2017). "The TAS2Rs with highest expression in HNSCC (TAS2R4, TAS2R14, TAS2R19, TAS2R20, TAS2R30, TAS2R43, and TAS2R45) overlap with TAS2Rs expressed at increased levels in breast cancer." (PMID 34717036, 2022). "The activation of TAS2R4 and TAS2R14 by quinine or apigenin led to a significant concentration-dependent reduction in cell proliferation of the breast cancer cell line MDA-MB-231, while proliferation of MCF-10A, the normal breast epithelial cells, was only attenuated at higher ligand concentrations." (PMID 34885005, 2021). "They characterised the expression of TAS2R1, TAS2R4, TAS2R10, TAS2R38 and TAS2R49 in those cells, finding that TAS2R4 is expressed at 40–70% in mammary epithelial cells in comparison to the commonly used breast cancer marker proteins, estrogen receptor and E-cadherin." (PMID 32708215, 2020). "For example, Singh and colleagues discovered the expression of TAS2R4 differed between metastatic breast cancer and non-cancerous epithelial cell lines, and Gaida and colleagues demonstrated the expression and localization of TAS2R38 in a pancreatic cancer cell line." (PMID 28467517, 2017).
dental caries (2 papers, 2021 to 2022). The decay of a tooth, in which it becomes softened, discolored, and/or porous. "Interestingly, findings from this study point to a protective effect of TAS2R4 variants against dental caries." (PMID 36404915, 2022). "This study also supported the role of taste receptor genes in dental caries (TAS2R38, TAS2R3, TAS2R4, TASR25), which have been associated with dental caries in previous studies." (PMID 34311721, 2021). "In summary, this study found multiple associations near genes that may play important roles in dental caries, such as TAS2R38, TAS2R3, TAS2R4, TASR25, DLX3 and DLX4, several of which have plausible biological functions relevant to tooth development and cariogenesis." (PMID 34311721, 2021). "An interesting suggestive association for the permanent dentition DFT was at 7q34 (lead SNP rs11197981; P = 1.11 × 10−6), approximately 200 kb downstream of taste receptor genes (TAS2R38, TAS2R3, TAS2R4, TASR25), which have plausible roles in dental caries." (PMID 34311721, 2021).
cervical squamous cell carcinoma (1 paper, 2022). A squamous cell carcinoma arising from the cervical epithelium. "Notably, statistically significant survival associations were identified for TAS2R5 in cervical squamous cell carcinoma (p < 0.001), TAS2R20 in esophageal adenocarcinoma (p = 0.044), and TAS2R4, TAS2R20, and TAS1R3 in prostate adenocarcinoma (p = 0.03, p = 0.033, and p = 0.023, respectively)." (PMID 35624283, 2022).
colon cancer (1 paper, 2024). "Utilizing univariate Cox regression analysis, we identified seven TAS2Rs genes associated with prognosis in colon cancer patients, including TAS2R4, TAS2R5, TAS2R14, TAS2R19, TAS2R20, TAS2R31, and TAS2R38." (PMID 38999959, 2024). "Our results show that compared to normal colon tissue, the expression levels of multiple bitter taste receptor genes are elevated in colon cancer tissue, including TAS2R4, TAS2R5, TAS2R14, TAS2R19, TAS2R20, TAS2R31, and TAS2R38." (PMID 38999959, 2024). "Differential expression analysis results revealed that compared to normal colon tissue, colon cancer samples exhibited elevated expression levels of TAS2R1, TAS2R4, TAS2R5, TAS2R14, TAS2R19, TAS2R20, and TAS2R38 (p < 0.05), with the exception of TAS2R60, which was downregulated." (PMID 38999959, 2024).
diabetes (1 paper, 2023). "The relationship between the variants of bitter taste receptor gene TAS2R4, dietary intake, and incidence of type 2 diabetes mellitus (T2DM) remains unclear." (PMID 36768516, 2023).
head and neck squamous cell carcinoma (1 paper, 2021). A squamous cell carcinoma that arises from any of the following anatomic sites: lip and oral cavity, nasal cavity, paranasal sinuses, pharynx, larynx, and salivary glands. "Additionally, higher mRNA level of TAS2Rs in total and in particular of TAS2R4 in tissue samples from head and neck squamous cell carcinoma were linked to a higher survival rate, supporting the in vitro results concerning the impact of TAS2Rs on cancer cell proliferation." (PMID 34885005, 2021). "Variably expressed TAS2Rs, including high levels of TAS2R4, 14, 19, 20, 30, 43 and 45, were detected in the investigated head and neck squamous cell carcinoma cell lines." (PMID 34885005, 2021).
Insulin resistance (1 paper, 2023). Increased resistance towards insulin, that is, diminished effectiveness of insulin in reducing blood glucose levels. "In the fully adjusted model, the TT genotype of TAS2R4 rs2233998 was significantly associated with fasting glucose levels, prevalence of insulin resistance, and increased risk of T2DM incidence in Korean women." (PMID 36768516, 2023).
cancer (3 papers, 2021 to 2025). A tumor composed of atypical neoplastic, often pleomorphic cells that invade other tissues. "Bitter taste receptors, including TAS2R4, have been implicated in the progression of various cancer types." (PMID 39886381, 2025). "It is worth noting that the activation of bitter taste receptors in cancer cells is predominantly associated with anti-cancer effects, and decreased expression of some TAS2Rs, such as TAS2R4, 5, 9, 10 or 14, is associated with poor prognosis, while increased expression counteracts carcinogenesis." (PMID 39886381, 2025). "Moreover, the activation of TAS2R targeted by denatonium benzoate, such as TAS2R4, 8, 10, 13, 39, 43, 46, 47, negatively impacted cancer cell physiology, motility, and cell proliferation, while the latter was caused by enhanced cell cycle arrest and apoptosis." (PMID 34885005, 2021).
tumor (2 papers, 2022 to 2024). "Changes in expression for TAS1R1, TAS1R3, TAS2R4, TAS2R5, TAS2R14, TAS2R19, and TAS2R20 had survival associations in at least one tumor histology." (PMID 35624283, 2022).
TAS2R4 also shares sentences with these, for which no sentence is quoted: papillary carcinoma (2 papers); esophageal adenocarcinoma (1); invasive breast carcinoma (1); kidney clear cell carcinoma (1); nasal polyp (1); pancreatic cancer (1); papillary thyroid carcinoma (1); prostate adenocarcinoma (1); type 2 diabetes mellitus (1).